TLR7 (toll like receptor 7)
Diseases named in the same sentence as TLR7 in open-access papers (continued):
Sharing a sentence is not in itself a finding about the gene and the disease.
asthma (continued). "Keeping with this, it was found that PBMCs of adolescents who suffer from asthma have low level of TLR7 expression and function and this might be a possible explanation for susceptibility to respiratory viral infections, which are a major cause of asthma exacerbations in children and adults." (PMID 29867994, 2018). "Therefore, normal TLR7 function may be protective against airway hyper-reactivity and asthma, whereas TLR7 polymorphism may predispose to asthma, and our observations suggest that the influence is greater in girls than in boys." (PMID 28592890, 2017). "Despite these challenges, our findings support the potential of TLR7/8 agonist 3M-052 as an immunomodulatory component for asthma therapy, with the EAIAD model providing a valuable platform to assess disease severity and immune polarization." (PMID 40951841, 2025). "In asthma patients infected with RV, IL-5 inhibits the function of pDCs and the expression of TLR7 by promoting the maturation and survival of eosinophils, thereby suppressing the antiviral response and leading to the exacerbation of asthma." (PMID 40636260, 2025). "Specifically, polymorphisms in both TLR7 and TLR8 were associated with eosinophil count, serum IgE levels, lung function, and asthma severity." (PMID 40672946, 2025). "Another study also showed that TLR7 expression is decreased in the lungs of patients with severe asthma." (PMID 38341589, 2024). "The ability of TLR7 signaling to promote an inflammatory response favoring Th1 immunity helps counteract the Th2-skewed imbalance observed in allergic or asthma models." (PMID 39769461, 2024). "In the merged dataset, the expression level of TLR7 in the asthma group significantly decreased compared with that of the healthy control group (p < 0.001)." (PMID 38341589, 2024). "Research reports that TLR7 agonists reduce Th2-mediated airway inflammation, airway hyperreactivity, and chronic airway remodeling in asthma." (PMID 38341589, 2024). "The expression levels of FCER1A and TLR‐9 in IL‐5‐ or IL‐17‐activated eosinophils and those of aryl hydrocarbon receptor and TLR‐7 in IL‐5‐activated eosinophils were significantly higher for patients with asthma than for normal individuals." (PMID 39575691, 2024). "The area under the curve of TLR7 for the diagnosis of asthma was 0.7674 (95% CI 0.631–0.904, p = 0.006)." (PMID 38341589, 2024). "After combining the results of LASSO, SVM-RFE, and hub genes, decreased TLR7 was finally identified as the core gene of asthma." (PMID 38341589, 2024). "Others have reported downregulation of Toll-like receptor 7 (TLR7) on AMs of asthma patients, suggesting defects in viral sensing and antiviral immunity." (PMID 38177117, 2024). "Bacterial and viral inflammation, signalling through TLR4 and TLR7/8, causes exacerbations of a range of different respiratory diseases, including COPD, asthma and ILDs, and plays a key role in the initiation of ARDS." (PMID 39137914, 2024). "ROC curve analysis was conducted to evaluate the sensitivity and specificity of TLR7 for the diagnosis of asthma." (PMID 38341589, 2024). "Regarding asthma, TLR2, TLR4, TLR7, TLR8, and TLR9 polymorphisms have been elucidated by their implication in allergic and asthma pathways and are also related to allergic and asthma exacerbations." (PMID 37920579, 2023). "Smooth muscle cell-specific knockout of Tet3 in mice leads to loss of intragenic 5-hydroxymethylcytosine, accumulation of spurious transcripts and TLR7/8-mediated lung inflammation resembling asthma in human lung samples." (PMID 36539616, 2023). "To further clarify the role of the TLR7-mast cell axis in COPD we used treatment with the anti-asthma and mastocytosis drug disodium cromoglycate (DSCG, cromolyn) that inhibits the release of mediators from mast cells." (PMID 37963864, 2023). "While TLR7 agonists are beneficial in asthma, TLR7 agonists are effective airway diaphoresis substances." (PMID 37090692, 2023).
asthma (continued). "It has been shown that IgE cross‐linking on pDCs and aberrant expression of microRNA in alveolar macrophages compromised TLR‐7 expression in asthma." (PMID 33236850, 2021). "Focusing on potential anti-allergic efficacy, local airway treatment with other TLR7 agonist have been employed in clinical trials in asthma and allergy." (PMID 34950134, 2021). "Preclinical work using murine models of asthma has shown the potential of synthetic TLR7/8 agonists to significantly reduce ovalbumin (OVA)-induced airway hyperreactivity and eosinophilic inflammation." (PMID 34058283, 2021). "Because pDCs is the major source of interferon‐α in PBMC,16, 17 the present study explored if the interferon‐α expression in pDCs was impaired under TLR‐7 or RV stimulation in asthma." (PMID 33236850, 2021). "Both TLR7/TLR8 polymorphisms have been associated with atopy and asthma, and Type 1 interferons have also been implicated making TLR7/8 agonists attractive compounds as adjuvants for AIT." (PMID 33281825, 2020). "These genes include asthma-related molecules ranging from pattern recognition receptors (e.g., Tlr7) to transcription factors (e.g., Foxp3)." (PMID 30677748, 2019). "TLR7 is known to be the most prominent TLR in eosinophils, as supported by TLR7-induced eosinophil activation in asthma, and activation of neutrophil upon TLR7 ligation in the eosinophilic cell line EoL-1." (PMID 31921842, 2019). "TLR7 has been also investigated and clinical studies support the protective effects of TLR7 in asthma since the TLR7 expression in bronchial epithelial biopsy of patients with severe asthma is markedly lower than healthy persons." (PMID 29867994, 2018). "In contrast, mice treated with allergen along with TLR7/8 ligand (R848) prevented asthma development." (PMID 29867994, 2018). "The role of TLR7 in murine experimental asthma and viral-induced asthma exacerbation has been also investigated." (PMID 29867994, 2018). "For example, we have previously shown that Tlr7-/- mice display the cardinal features of asthma following an earlier life and later life infection with pneumonia virus of mice (PVM; a murine analogue of RSV)." (PMID 28099113, 2017). "TLR7 stimulation suppresses eosinophilic airway inflammation in a variety of animal models of asthma through reducing Th2 cytokines such as IL-4 and IL-5 as well as eotaxin in the lung and IgE." (PMID 27274620, 2016). "Several synthetic small TLR7 agonists have been studied for their potential use to treat asthma, but with limited benefits because of local and systemic inflammatory reactions." (PMID 27014274, 2016). "There was no change in IL-13 levels or numbers of mucus-producing cells, suggesting a novel and critical role of TLR7 signalling in RV-induced asthma exacerbation." (PMID 26108570, 2015). "The expressions of TLR5 and TLR7 are decreased in the epithelium of patients with severe asthma compared with healthy individuals and those with moderate asthma." (PMID 26617525, 2015). "Recently, SNPs of both TLR7 & TLR8 have been identified and found to be associated with asthma, rhinitis and atopic dermatitis." (PMID 24819048, 2014). "Taken together our novel severe asthma model shows a very strong remodeling phenotype which is steroid insensitive and only partially sensitive to TLR7 and TLR9 agonist treatment." (PMID 24618687, 2014). "In conclusion we have developed a severe asthma model, which is steroid resistant and only partially sensitive to TLR7 and TLR9 agonist treatment." (PMID 24618687, 2014). "This increased responsiveness of R848 in the asthmatic cells is also surprising in the context of previous reports of reduced TLR7 function in PBMCs in asthma and in pregnancy and should be interpreted with caution." (PMID 23824215, 2013). "Taken together, these results suggest that TLR7 activation promotes resolution of inflammation in experimental asthma." (PMID 23584892, 2013).
asthma (continued). "All these findings illustrate that TLR3 and TLR7 in immune organs play a vital role in the development of asthma." (PMID 21364926, 2011). "Nevertheless, a recent study has been reported that application of TLR2, TLR3, TLR4 and TLR7 agonists all show a protective effect for asthma." (PMID 21364926, 2011). "For example TLR7 and TLR8 are associated with human asthma while ligands of TLR7 and TLR8 can prevent airway remodeling caused by experimentally induced asthma." (PMID 21108806, 2010). "Importantly, the administration of a TLR7 agonist reversed these detrimental effects, suggesting that TLR7 upregulation mitigates asthma inflammation by inhibiting the NF-κB signaling pathway." (PMID 40672946, 2025). "In a mouse asthma model induced by dust mites, TLR7 expression was significantly downregulated." (PMID 40672946, 2025). "employed a combined analysis approach based on the gene expression profiles of induced sputum derived from the comprehensive Gene Expression Omnibus databases (GSE76262 and GSE137268) and found that reduced TLR7 expression correlated with airway eosinophilic inflammation and lung function in asthma." (PMID 40672946, 2025). "Finally, the expression level of TLR7 was validated in induced sputum samples of patients with asthma." (PMID 38341589, 2024). "Finally, the decreased TLR7 expression levels were validated in induced sputum samples of patients with asthma." (PMID 38341589, 2024). "Of these receptors, TLR2 and TLR7 play an important role in the pathogenesis of asthma." (PMID 36636604, 2023). "Thus, TLR7 agonists, as well as LAMA, are expected to have an effect on regulating asthma exacerbation, especially those associated with viral infection." (PMID 35911708, 2022). "Several lines of evidence supported the association between SLE and TLR7 SNPs in various populations, while additional studies found correlation between TLR7 polymorphisms and susceptibility to HCV and chikungunya virus infection, asthma, and age-related macular degeneration." (PMID 33763088, 2021). "Our objective in this study was to determine whether the innate response of pDCs to TLR‐7 and RV is defective in patients with asthma." (PMID 33236850, 2021). "We recently discovered that activation of TLR7/8 resulted in enhanced IFNλ receptor mRNA expression in PBMCs of healthy and asthmatic children, opening new therapeutic frontiers for rhinovirus-induced asthma." (PMID 34899691, 2021). "Our laboratory has been interested in interactions between TLR7 and peripheral nerves in the lungs given that RNA respiratory viruses potentiate nerve-mediated bronchoconstriction and are a common trigger for asthma exacerbations in humans." (PMID 34530852, 2021). "TLR7 expression was also reportedly increased in severe asthma." (PMID 34530852, 2021). "While as an association was seen between TLR7 rs179009AG genotype and acquisition of HIV-1 (OR = 0.42, P = 0.016), TLR7rs179008A/T polymorphism was associated with susceptibility to asthma, course of hepatitis C infection, HIV-1 acquisition, and disease progression." (PMID 32565728, 2020). "In animal models of asthma, TLR7 agonism downregulates T2 airway inflammation." (PMID 33166307, 2020). "The interaction of genes, including CD1(c, e, a) and TLR7, in the transition to the severity of asthma could be correlated with its previously published roles in the severity of asthma." (PMID 32512817, 2020). "AZD8848 is a novel TLR7 agonist being developed for the treatment of asthma and allergic rhinitis." (PMID 31856838, 2019). "Importantly, the suppressive effect on asthma by TLR7 agonists was also obtained when administered by intraperitoneal or epicutaneous routes." (PMID 29867994, 2018). "Interestingly, simultaneous engagement of TLR3 and TLR7 by viral components prevented airway hyperresponsiveness and suppressed established asthma." (PMID 29867994, 2018).
asthma (continued). "We evaluated whether post-bronchiolitis asthma was associated with polymorphisms in the TLR3 rs3775291, TLR4 rs4986790, TLR7 rs179008, TLR8 rs2407992, TLR9 rs187084, and TLR10 rs4129009 genes." (PMID 28592890, 2017). "Moreover, PVM challenge of TLR7−/− mice in later-life induces an asthma-like pathology including type-2 cytokine production, airway eosinophilia and ASM remodelling." (PMID 28539639, 2017). "TLR7-deficient mice displayed reduced IFN secretion, increased virus replication, and increased eosinophilic inflammation and AHR, indicating that impaired TLR7 expression on pDCs by allergic inflammation exaggerates asthma exacerbations." (PMID 28848549, 2017). "Genetic studies have also linked TLR7 and TLR8 polymorphisms to increased risk of asthma." (PMID 26477783, 2016). "Intracellular TLRs agonists such as TLR7/TLR8 agonists have also been evaluated in asthma." (PMID 27274620, 2016). "Asthma exacerbations represent a significant disease burden and are commonly caused by rhinovirus (RV), which is sensed by Toll-like receptors (TLR) such as TLR7." (PMID 26108570, 2015). "This implicates IL-5-induced airways eosinophilia as a negative regulator of TLR7 expression and antiviral responses, which provides a molecular mechanism underpinning the effect of eosinophil-targeting treatments for the prevention of asthma exacerbations." (PMID 26108570, 2015). "In severe asthma, allergen challenge increased Tlr7 expression." (PMID 23781124, 2013). "Interestingly, different groups demonstrated effectiveness of TLR7 triggering to suppress allergic airway inflammation in experimental asthma models suggesting immunomodulatory potential of synthetic TLR7 ligands." (PMID 22927956, 2012). "AZD8848/DSP-3025 is a novel TLR7 agonist being tested for the treatment of asthma and hay fever." (PMID 23151919, 2012). "To further determine the role of down-regulated TLR7 on asthma development, we investigated whether TLR7 agonist could affect AIPI development." (PMID 21364926, 2011). "In fact, several studies have reported that TLR7 agonists could attenuate the symptom of experimental asthma and virus-induced airway dysfunction." (PMID 21364926, 2011). "Interestingly, TLR7 expression in immune cells is reduced in patients with asthma." (PMID 40083723, 2025). "Therefore, it could be concluded that TLR7 may play a critical role in asthma by regulating immune cells." (PMID 38341589, 2024). "Our study discovered the response to TLR‐7 stimulation in pDCs was compromised and the sustainability of interferon‐a expression to RV stimulation was reduced in pDCs of asthmatic patients, which provide further evidence of defective innate response and subspeciality to RV infection in asthma." (PMID 33236850, 2021). "Our study discovered the response to TLR‐7 stimulation in pDCs was compromised and the sustainability of interferon‐α expression to RV stimulation was reduced in pDCs of asthmatic patients, which provide further evidence of defective innate response and subspeciality to RV infection in asthma." (PMID 33236850, 2021). "It is not known to what extent the present profile of action of imiquimod is shared with other TLR7 agonists, including two drugs that already have been subjected to clinical trials to determine anti-allergic efficacy by local airway administration in asthma and rhinitis." (PMID 34950134, 2021). "In addition to their utility as potential anti-viral compounds, synthetic TLR7/8 agonists are being explored as agents to shift the polarization of immune response and as bronchodilators for treatment of allergic conditions such as asthma and rhinitis." (PMID 34058283, 2021). "Although no further studies are currently planned with GSK2245035, future development of a TLR7 modulator may be beneficial via an alternative route and or therapeutic indication, such as inhaled route for asthma and intranasal route for immunotherapy adjuvant." (PMID 33166307, 2020).
asthma (continued). "The present study was carried out to complement this exploratory study series by evaluating whether the TLR3 rs3775291, TLR4 rs4986790, TLR7 rs179008, TLR8 rs2407992, TLR9 rs187084, and TLR10 rs4129009 polymorphisms are associated with post-bronchiolitis asthma." (PMID 28592890, 2017). "This is directly relevant to subjects with moderate-to-severe asthma with a predominantly eosinophilic airways inflammation as these individuals have suppressed—but not fully deficient—TLR7 expression in their lungs, which correlated with reduced IFN expression." (PMID 26108570, 2015). "Hence TLR7 in spleen may play a key role in the development of asthma via IL-4 to induce the production of allergen-specific IgE by B cells." (PMID 21364926, 2011). "Consistently, the TLR7 expression level in the asthma group of the GSE147878 dataset also significantly decreased (p < 0.01), and the AUC value of TLR7 was 0.783 (95% CI 0.645–0.897)." (PMID 38341589, 2024). "TLR7 agonists can increase the expression of interferon and C-C motif chemokine ligand 13 (CCL13) in nasal mucosa of patients with asthma and allergic rhinitis." (PMID 38341589, 2024). "Other TLR7 agonists, AZD8848 and GSK2245035, have been evaluated as therapeutic agents in clinical trials for asthma." (PMID 35911708, 2022). "The CD1C, TLR7, PTK2, CD1E, CD1A, and ERBB2 genes had a higher rate of engaging protein interactions in the PPI for the moderate-to-severe asthma phenotype." (PMID 32512817, 2020). "pDCs present an attractive target for the prevention of severe RSV-bronchiolitis and asthma due to their capacity to produce vast amounts of type I IFN via engagement of TLRs (e.g., TLR7) and promote Treg cell expansion." (PMID 28261214, 2017). "Resiquimod is a typical TLR7/TLR8 agonist and in vivo suppresses AHR as well as airway remodeling in asthma." (PMID 27274620, 2016). "We chose to use dexamethasone, TLR7 (resiquimod; R848) and TLR9 (CpG-ODN) agonists because all three have been previously shown to have potent anti-allergic effects in animal models of asthma." (PMID 24618687, 2014). "This chronic model is steroid insensitive and less sensitive to therapeutic intervention with the TLR7 and TLR9 agonist resiquimod or CpG-ODN than other published severe asthma models." (PMID 24618687, 2014). "This list included many genes with a purported role in regulation of the immune response in asthma: interleukins (IL2IL27 and IL33), chemokines (CXCL1CXCL17CCL5 and CCL27), mucins (MUC2MUC13 and MUCL1), TLR7 and NOS2, among others." (PMID 22713245, 2012). "In addition, ISS from asthma patients also had an activation effect on TLR3, TLR7, and TLR8, which play crucial roles in immune regulation." (PMID 39950864, 2025). "This suggests that genetic variations in TLR7 and TLR8 may indeed contribute to asthma pathogenesis, particularly influencing disease characteristics rather than initial susceptibility." (PMID 40672946, 2025). "Estrogen can activate immune genes such as TLR7/TLR8 on the X chromosome, enhance eosinophil infiltration, and promote IL-13-mediated mucus secretion, making female asthma patients more prone to hormone-dependent acute exacerbations (e.g., during menstrual periods or perimenopause)." (PMID 41244254, 2025). "The expression levels of IL17RA, IL4RA, integrin β2, CCR3, FCER1A, TGFB1, TLR‐3, TLR‐7, and TLR‐9 in eosinophils treated with IL‐17 for 3 h were higher for normal individuals than for patients with asthma." (PMID 39575691, 2024). "Second, our sample size was small and we did not compare TLR7 protein levels across different asthma subtypes." (PMID 38341589, 2024). "In addition, similar to asthma, increased responsiveness of CCL13 to TLR7/8 agonists has also been observed in allergic rhinitis." (PMID 37153575, 2023). "have previously demonstrated that TLR7 activation on pDCs induces the release of IFN-α, which in turn will inhibit the proliferation and cytokine production in ILC2 cells, key mediators of asthma pathogenesis." (PMID 34950134, 2021).